NLRC4 (NLR family CARD domain containing 4)
Diseases named in the same sentence as NLRC4 in open-access papers (continued):
Sharing a sentence is not in itself a finding about the gene and the disease.
infection (continued). "For example, studies employing wild-type S. Tm infections showed that the epithelial NAIP/NLRC4 inflammasome and downstream effectors (e.g., GSDMD) are crucial for preventing destructive inflammation in 72 h S. TmWT infection." (PMID 41370284, 2025). "We infected primary bone marrow-derived macrophages (BMDMs) from Nlrc4−/− mice, which are permissive to flagellated L. pneumophila, and quantified CFU over 72 h of infection." (PMID 36598225, 2023). "The Achromobacter strains induced pyroptosis by engaging either the NLRC4 or NLRP3 sensors, as demonstrated by infections in THP-1 cells with single and double knockouts in these sensors." (PMID 37598340, 2023). "Nlrc4-/- neutrophils incubated with MCC950 responded the same as C57BL/6 neutrophils, i.e., MCC950 inhibited IL-1β following infection with PAO1 or ExoS ADPRT expressing mutants." (PMID 37730693, 2023). "In the current study, we characterized the relative contributions of T3SS, the NLRP3 versus the NLRC4 inflammasomes, and GSDMD and GSDME to IL-1β release and pyroptosis in neutrophils versus macrophages following infection with P. aeruginosa." (PMID 37730693, 2023). "To test our hypothesis, we first evaluated the dependence of PKCδ and NLRC4 phosphorylation and NLRC4 inflammasome activation on Crk in response to P. aeruginosa, by depleting BMDMs of Crk adaptor protein by Crk-specific siRNA9,82 prior to infection with P. aeruginosa." (PMID 35277504, 2022). "Importantly, IL-1β release was entirely dependent on NLRC4 upon infection with any of these different Pseudomonas aeruginosa strains, whereas the pyroptotic strains PAO1ΔExoS, CHAΔExoS and PP34ΔExoU triggered neutrophil lysis and IL-1β release that was fully NLRC4-dependent." (PMID 35849616, 2022). "Rather, we found that infection of human macrophages with Salmonella grown under SPI-1-inducing conditions activates multiple inflammasomes, including NAIP/NLRC4, CASP4/5, and NLRP3." (PMID 35073381, 2022). "We find that although the NAIP/NLRC4 inflammasome is essential for detecting T3SS ligands in human macrophages, it is partially required for responses to infection, as Salmonella also activated the NLRP3 and CASP4/5 inflammasomes." (PMID 35073381, 2022). "At 6 or 24 hours post-infection, the bacterial burden was the lowest in WT THP-1s, whereas NAIP-/- and NLRC4-/- THP-1s harbored significantly higher bacterial burdens." (PMID 35073381, 2022). "Collectively, these data suggest that both the NAIP/NLRC4 and NLRP3 inflammasomes control intracellular Salmonella replication within human macrophages at both early (6 hours post-infection) and late (24 hours post-infection) timepoints." (PMID 35073381, 2022). "During infection, the P. aeruginosa T3SS needle tip complex and flagellin are the major PAMPs that activate the NLRC4 inflammasome (35, –, 38)." (PMID 35130452, 2022). "The bacterial burden of ΔprgIfliCfljB over a 24-hour post-infection time course was controlled the most effectively in WT THP-1s and was significantly less restricted in NAIP-/- and NLRC4-/- THP-1s." (PMID 35073381, 2022). "In human and murine macrophages, NAIP/NLRC4 and NLRP3 are triggered to form inflammasomes upon infection with S. Typhimurium." (PMID 33380493, 2021). "Macrophages infected with B. thailandensis undergo NLRP3-, NLRC4-, caspase-1-, caspase-11-, and GSDMD-dependent pyroptosis (52, –, 60), but the role of other cell death pathways during infection is poorly understood." (PMID 34154417, 2021). "By imaging infections in 3D-, 2D-, and chimeric enteroids, we mapped NAIP/NLRC4-driven cell death features in both space and time." (PMID 33731826, 2021). "Common PRRs of NOD1, NOD2, NLRP3, NLRC4, NLRC5, and AIM2 were detected using qPCR assays after 90 min of infection with A. sobria at a MOI of 10 and 2 h gentamycin treatment followed by 12 h incubation." (PMID 34513725, 2021). "In THP-1 cells, NAIP/NLRC4 and NLRP3 played redundant roles in inflammasome activation during infection with S. Typhimurium." (PMID 33380493, 2021).
infection (continued). "Salmonella Enteritidis (SE) is one of the major foodborne zoonotic pathogens of worldwide importance which can induce activation of NLRC4 and NLRP3 inflammasomes during infection." (PMID 32723297, 2020). "NLRP3 is a classic sensor and has been reported to drive GSDMD cleavage in response to pathogen infection; therefore, we investigated the roles of the newly discovered NLRs NLRP12 and NLRC4." (PMID 32295623, 2020). "Infection of monocytes with S. Typhimurium activates the NLRP3 inflammasome, whereas in macrophages both NLRP3 and NLRC4 are activated." (PMID 32185892, 2020). "Upon infection of mouse or human macrophages, L. monocytogenes can be detected by multiple inflammasomes, including AIM2, NLRC4, NLRP3, NLRP6, caspase‐11 and NLRP1B." (PMID 32185892, 2020). "UPEC significantly decreased the gene expression of CASP4, NLRP1, NLRC4, NLRP6 and AIM2 at MOI 1 and MOI 10 after 3 h of infection compared to unstimulated cells." (PMID 33318544, 2020). "To visualize the NLRC4 participation in inflammasome activation, we once again performed MDM infection with Mtb H37Rv assays and stained the specks using specific antibodies." (PMID 33193317, 2020). "A clear upregulation of NLRC4 and NAIP in THP-1m upon CFT073 infection was seen as compared to resting macrophages (mock)." (PMID 31551961, 2019). "SPI-2 mutation also resulted in increased expression of SPI-1 effectors detectable by NLRC4 (FljB, PrgI, and PrgJ), suggesting that SPI-2 activity helps suppress the translocation of SPI-1 effectors later in infection." (PMID 31402916, 2019). "In response to pathogen infection and tissue damage, pattern recognition receptors (PRRs) (NLRP3, NLRC4) oligomer is formed and it can recruit ASC." (PMID 31133717, 2019). "Infection with Burkholderia pseudomallei or B. thailandensis triggers activation of the NLRP3 and NLRC4 inflammasomes leading to release of IL-1β and IL-18 and death of infected macrophages by pyroptosis, respectively." (PMID 29791511, 2018). "In comparison with wild-type bacteria, infection with the complemented PA14 ΔflgK pUCP19-flgK and PA14 ΔpopB pUCP19-popB strains restored to varying degrees the protein levels of TLR4, TLR5, NLRC4, caspase-4 and mature IL-1β and IL-18." (PMID 28469996, 2017). "On assessing NLRP3 or NLRC4 gene or protein expression, it was found that NLRP3 expression was robust during the first week of either infection with a decline thereafter." (PMID 26972847, 2016). "The Nlrc4 inflammasome detects the cytosolic presence of bacterial flagellin during infection using NLR family, apoptosis inhibitory protein 5 (Naip5), and NLR family, CARD domain containing 4 (Nlrc4) to form a heterooligomeric inflammasome structure." (PMID 26635450, 2015). "In serum 24 hours after infection, TNF-α, MIP-2, and Il-1β levels were low but KC was readily detectable and higher in Nlrc4−/− mice compared to Casp1−/−Casp11−/− mice." (PMID 25232720, 2014). "They demonstrated that both NLRC4 and NLRP3 knockout macrophages can cleave caspase-1 as wild-type macrophages eight hours after infection." (PMID 24626296, 2014). "Here, we demonstrate that infection with V. parahaemolyticus triggers both NLRP3- and NLRC4-inflammasome activation." (PMID 23357873, 2013). "Conversely at 24 hours post infection, TNF levels were consistently enhanced in Nlrc4−/−/Tlr5−/− mice when compared to Nlrc4−/− or WT mice." (PMID 23937571, 2013). "To identify the NLR involved in IL-1β secretion, we infected bone marrow-derived wild type (wt) and knockout macrophages in NLRC4, NLRP3, ASC and Caspase-1 (all from C57BL/6 mice background) at MOI of 50 and quantified the IL-1β produced 24 h post-infection." (PMID 22848580, 2012). "We next assessed the role of NLRC4 and NLRP3 in protection from systemic dissemination of infection." (PMID 22174673, 2011). "Infection of macrophages with Listeria monocytogenes induces the activation of caspase-1 via NLRP3, NLRC4 and AIM2 inflammasomes." (PMID 22019906, 2011).
infection (continued). "We observed substantial levels of GSDMD-dependent cell death in mT3Sf-infected CASP4–/– cells (mediated by NLRC4) and in NLRC4–/– cells (mediated by CASP4), confirming that mT3Sf::empty infection induces pyroptosis via activation of both of these two main cell death pathways." (PMID 41533441, 2026). "In these Nlrc4−/− mice, which cannot control epithelial S. Tm loads, increased lamina propria TNF-α levels drive barrier dislodgement by day 3 post infection, indicating that the NAIP/NLRC4 inflammasome is also required to prevent late-stage barrier disruption." (PMID 40796289, 2025). "NLRC4 (formerly known as IPAF, Card12) can form an inflammasome following infection with various gram-negative bacteria, such as S. typhimurium, Legionella pneumophila, Shigella flexneri, and Pseudomonas aeruginosa." (PMID 38566180, 2024). "Even during infection with flagellin-deficient L. pneumophila, which does not induce NAIP5/NLRC4 activation, we observed significant induction of L. pneumophila-triggered cell death following TNF priming." (PMID 37279255, 2023). "In contrast, macrophages from phosphomimetic mutant Nlrc4S533D/S533D mice, that harbors a constitutive phosphorylation on NLRC4 Ser 533, did not demonstrate any resistance to the infection." (PMID 38124741, 2023). "We conclude that NLRC4-dependent pyroptosis in macrophages is neither a major driver of disease pathogenesis nor bacterial colonization in our oral mouse model of infection." (PMID 36645406, 2023). "In NLRC4 KO, NLRP3 KO, and WT THP-1 cells, GSDMD cleavage occurred even when the axoU gene was disrupted, while in the NLRC4/NLRP3 KO THP-1 no pyroptosis occurred upon infection with wildtype or AC055pGPI-axoU." (PMID 37598340, 2023). "Using this priming and infection model alongside genetic tools, we demonstrate that TNF signaling through TNFR1 licenses L. pneumophila-infected cells to rapidly and robustly undergo cell death independently of flagellin and the NAIP/NLRC4 inflammasome." (PMID 37279255, 2023). "Results from our experiments with treatment of BMDMs with CA and ∆yopK Yptb mutant infection showed that there was a nonsignificant decrease in IL-1β release which can be attributed to the inhibition of NLRP3 but not of the NLRC4 inflammasome." (PMID 37787552, 2023). "Furthermore, NAIP-/- and NLRC4-/- THP-1s treated with MCC950 secreted negligible levels of IL-1α, IL-1β, and IL-18, similar to those observed during ΔsipB Stm infection." (PMID 35073381, 2022). "Among the different tested neutrophil genotypes, significant resistance to pyroptotic cell lysis (LDH release) was only observed in Casp1-/-, Casp1-/-Casp11-/-, Nlrc4-/- and ASC-/- BMNs upon infection with P. aeruginosa pyroptotic strains PAO1ΔExoS and PP34ΔExoU." (PMID 35849616, 2022). "Intriguingly, Abl co-immunoprecipitated with PKCδ but not with NLRC4 in response to infection with P. aeruginosa." (PMID 35277504, 2022). "While PKCδ and NLRC4 co-immunoprecipitated with each other in response to infection as expected, neither protein co-immunoprecipitated with CrkI or CrkII isoforms of Crk, suggesting that Crk functions upstream of PKCδ phosphorylation." (PMID 35277504, 2022). "We show that during infection with P. aeruginosa and in response to T3SS, Abl tyrosine kinase interacts with PKCδ and this interaction is required for PKCδ phosphorylation and for NLRC4 inflammasome activation." (PMID 35277504, 2022). "Nlrc4-/- BMNs had improved ability to restrict PAO1, PP34ExoUS142A and PAO1ΔExoS infection than WT and Pad4-/- neutrophils, suggesting that neutrophil pyroptosis more than PAD4-driven DNA decondensation promotes neutrophil failure to restrict PAO1, PP34ExoUS142A and PAO1ΔExoS." (PMID 35849616, 2022). "NAIP-/- and NLRC4-/- THP-1s treated with CASP5 siRNA showed a slight but significant decrease in IL-1β secretion following CASP5 siRNA treatment, but not CASP4 siRNA treatment, compared to control siRNA-treated cells following WT Stm infection." (PMID 35073381, 2022).
infection (continued). "To assess the role of Abl kinase in NLRC4 inflammasome activity in response to P. aeruginosa infection in wound, we treated C57BL/6 mice with Abl inhibitor Imatinib or PBS by intraperitoneal injection, prior to wounding and infection with P. aeruginosa." (PMID 35277504, 2022). "Although NLRC4 mediates IL-1β secretion following infection with other Gram-negative pathogens, we consider it unlikely that KP activates NLRC4 because KP does not express any of the bacterial proteins known to activate this inflammasome." (PMID 35947948, 2022). "Previous work in mouse models of infection reported that both the Naip/NLRC4 inflammasome and the caspase-11 noncanonical inflammasome participate in the immune response against Burkholderia." (PMID 34399626, 2021). "Its NAIP/NLRC4 inflammasome senses infection by Gram-negative bacteria, including Salmonella Typhimurium (S.Tm) and promotes expulsion of infected enterocytes." (PMID 33731826, 2021). "On the opposite, LPS-primed U937 expressing NLRP3 S806A, D, or E mutants secreted IL-1β as WT U937 in response to infection by Salmonella enterica serovar Typhimurium (SL1344 strain) and transfection with poly(dA:dT), activating the NLRC4 and AIM2 inflammasomes respectively." (PMID 34615873, 2021). "To trace the onwards progression of the infection in the presence or absence of NAIP/NLRC4, we extended our kinetic experiments to the 24–72 h p.i. window." (PMID 33731826, 2021). "129.Nlrc4–/– mice also exhibited dramatic cecum shrinkage and diarrhea, lost between 8% and 18% of their starting weight within 2 days of infection, and exhibited a massive increase in fecal MPO following infection." (PMID 33074100, 2020). "Nevertheless, in our iv infections, Caspase-1 mediated defense appears independent of NLRC4, NLRP3, or Caspase-11." (PMID 31953493, 2020). "This could explain why infection events are efficiently sensed and restricted specifically by IEC NAIP/NLRC4." (PMID 31953493, 2020). "Also, because ExoU can inhibit the NLRC4 inflammasome and caspase-1, the level of IL-1β production would be expected to be higher after infection with PAO1 than after infection with PA103." (PMID 30455194, 2019). "The role of ASC in the response of NLRC4 to infection has been explored in murine gram-negative infection models, including S typhimurium, P aeruginosa, Legionella pneumophila, and Shigella species." (PMID 29778503, 2018). "The inflammasome activation in the absence of NLRC4 during P. aeruginosa infection is not strain-dependent as the same was observed during infection with P. aeruginosa strains PA01 and PAK." (PMID 30062052, 2018). "After 6 h of hCFs infection with wild-type PAO1 and PA14, significant levels of TLR4, TLR5, NLRC4, native form of caspase-4 and IL-1β and IL-18 mature-formed proteins were detected by western blot with quantification of protein densitometry ratios relative to endogenous β-actin." (PMID 28469996, 2017). "To define the inflammasome complexes that contribute to IL-1β secretion following infection with virulent IOE and regulated by MyD88, we further analyzed mRNA expression of several inflammasome complexes (NLRP3, NLRC4, AIM2) in the liver tissues of WT and MyD88-/- mice on day 7 p.i with IOE." (PMID 29049365, 2017). "Pyruvate did not prevent inflammasome formation or cell death induced by infection with S. typhimurium in log phase growth, an infection model that activates the NLRC4 inflammasome." (PMID 27011353, 2016). "We have not found any evidence of neutrophil cell death during infection of larvae with ST, being this in agreement with a recent study reporting that neutrophils do not undergo pyroptotic cell death on NLRC4 and caspase-1 activation." (PMID 27363812, 2016). "Although YopM inhibits a pathway dependent on Asc and caspase-1, we observed no decrease of IL-1β in cells lacking NLRP3, NLRC4, or caspase-11 compared to wild-type cells after infection with Y. pestis lacking YopM." (PMID 27911947, 2016).
infection (continued). "Confirming what we observed during infection with B. pseudomallei, production of IL-1β following infection with B. thailandensis was dependent on NLRP3, ASC, and caspase-1 while pyropotosis was dependent on NLRC4." (PMID 25166912, 2014). "NLRC4 (formerly known as IPAF, Card12) has been shown to form an inflammasome upon infection of macrophages with various gram-negative bacteria such as Salmonella typhimurium, Legionella pneumophila, Shigella flexneri and Pseudomonas aeruginosa." (PMID 23666718, 2013). "Even though less pronounced, Nlrc4−/− macrophages also secreted lower levels of IL-1β during infection with WT L. monocytogenes, most likely due to the lack of endogenous L. monocytogenes flagellin recognition by NLRC4." (PMID 24058709, 2013). "Under low MOI infection conditions where there is minimal induction of pyroptosis, it was revealed that the induction of autophagy dampens pyroptosis in response to L. pneumophila, and turnover of autophagosomes requires NAIP5, NLRC4, and caspase-1." (PMID 24409420, 2013). "NLRC4 regulates Caspase-1 activation and IL-1β processing in response to infection with various gram-negative bacteria." (PMID 22701621, 2012). "We posit that this pattern likely reflects the fact that the NLRC4 inflammasome responds to T3SS deployment, which occurs early in the infection cycle, while activation of NLRP3 may require escape from the phagosome, which is a relatively slower event." (PMID 22241982, 2011). "However, in those infection models NLRP3 and NLRC4 appeared to play redundant roles while in our model we were able to assign distinct functions to each inflammasome." (PMID 22241982, 2011). "Measurement of the bacterial burdens in lungs, spleens, and livers of infected mice 24 hours (data not shown) and 48 hours post-infection revealed that Nlrc4-/- and Casp1-/- mice carried considerably higher burdens in all three organs than WT mice." (PMID 22241982, 2011). "Additionally, our data suggest that the inflammasome protein NLRC4 does not play a significant role in the infection." (PMID 37365163, 2023). "Interestingly, unlike macrophages, neutrophils infected with S. thyphimurium activate the NLRC4 inflammasome, but the infection does not induce inflammasome-dependent pyroptosis." (PMID 37006312, 2023). "Infection with S. typhimurium induced phosphorylation in NLRC4 at serine 533 which could not be prevented by CASP1 inhibition, clearly suggesting that this phosphorylation event occurred upstream of CASP1 cleavage." (PMID 34276697, 2021). "In addition to the role of NLRC4 in immune cells from the hematopoietic compartment during this infection, NLRC4 activation in the non-hematopoietic cellular compartment also occurs, especially in gut epithelial cells." (PMID 33494299, 2021). "Both NLRC4 and non-canonical inflammasome activation play a role in epithelial cell responses to infection, and may help reduce bacterial dissemination throughout the intestinal mucosa." (PMID 31402916, 2019). "Infection of A/E pathogens, such as EPEC and EHEC, might activate NLRC4 and NLRP3 inflammasomes." (PMID 26332984, 2015). "For B. pseudomallei, it has been suggested, that the NLRC4 inflammasome responds to T3SS3 deployment, which takes place early in the infection cycle, whereas activation of the NLRP3 inflammasome might require escape from the phagosome, which probably occurs later." (PMID 24626296, 2014). "Importantly, infection with the non-flagellated bacteria S. flexneri also induces NLRC4-mediated pyroptosis, most likely in response to the inner rod component of T3SS." (PMID 25071770, 2014). "The biological importance of effector-mediated NLRC4 suppression during in vivo infection with V. parahaemolyticus remains to be elucidated because of the lack of an oral infection model in mice capable of evoking bacterial colonization and inflammation in intestine." (PMID 23357873, 2013).